CCDC88A (coiled-coil and HOOK domain protein 88A)
Description:
Bifunctional modulator of guanine nucleotide-binding proteins (G proteins). Acts as a non-receptor guanine nucleotide exchange factor which binds to and activates guanine nucleotide-binding protein G(i) alpha subunits. Also acts as a guanine nucleotide dissociation inhibitor for guanine nucleotide-binding protein G(s) subunit alpha GNAS. Essential for cell migration. Interacts in complex with G(i) alpha subunits with the EGFR receptor, retaining EGFR at the cell membrane following ligand stimulation and promoting EGFR signaling which triggers cell migration. Binding to Gi-alpha subunits displaces the beta and gamma subunits from the heterotrimeric G protein complex which enhances phosphoinositide 3-kinase (PI3K)-dependent phosphorylation and kinase activity of AKT1/PKB. Phosphorylation of AKT1/PKB induces the phosphorylation of downstream effectors GSK3 and FOXO1/FKHR, and regulates DNA replication and cell proliferation (By similarity). Binds in its tyrosine-phosphorylated form to the phosphatidylinositol 3-kinase (PI3K) regulatory subunit PIK3R1 which enables recruitment of PIK3R1 to the EGFR receptor, enhancing PI3K activity and cell migration. Plays a role as a key modulator of the AKT-mTOR signaling pathway, controlling the tempo of the process of newborn neuron integration during adult neurogenesis, including correct neuron positioning, dendritic development and synapse formation (By similarity). Inhibition of G(s) subunit alpha GNAS leads to reduced cellular levels of cAMP and suppression of cell proliferation. Essential for the integrity of the actin cytoskeleton. Required for formation of actin stress fibers and lamellipodia. May be involved in membrane sorting in the early endosome. Plays a role in ciliogenesis and cilium morphology and positioning and this may partly be through regulation of the localization of scaffolding protein CROCC/Rootletin.
Synonyms: APE; GIV; HkRP1; GRDN; KIAA1212; FLJ10392; GIRDIN; PEHO; PEHOL
Tractability: Small molecule: a structure with a bound ligand is known. Antibody: UniProt places it where antibodies can reach, with high confidence; its Gene Ontology location is reachable by antibodies, with high confidence; the Human Protein Atlas places it where antibodies can reach. PROTAC: ubiquitination databases record sites on it; its protein half-life has been measured.
Gene: Protein-coding gene on chromosome 2 (55,287,818 to 55,420,042, reverse strand). Ensembl gene ENSG00000115355.
Subcellular location: Cell membrane; Cytoplasm, cytosol; Cytoplasmic vesicle; Cell projection, lamellipodium; Cytoplasm, cytoskeleton, cilium basal body; Cytoplasm, cytoskeleton, microtubule organizing center, centrosome, centriole
Subcellular location (Human Protein Atlas): Basal body; Centrosome; Nucleoplasm; Plasma membrane
Pathways (Reactome):
Signal Transduction: RND1 GTPase cycle; RND3 GTPase cycle
Gene Ontology:
Molecular function: actin binding; epidermal growth factor receptor binding; G-protein alpha-subunit binding; GDP-dissociation inhibitor activity; guanyl-nucleotide exchange factor activity; insulin receptor binding; phosphatidylinositol binding; protein homodimerization activity; protein kinase B binding; protein kinase C binding; SH2 domain binding; vascular endothelial growth factor receptor 2 binding; dynein light intermediate chain binding; microtubule binding; protein serine/threonine kinase activator activity
Biological process: activation of protein kinase activity; cell migration; lamellipodium assembly; maintenance of protein location in plasma membrane; membrane organization; positive regulation of cilium assembly; positive regulation of epidermal growth factor receptor signaling pathway; positive regulation of protein localization to cilium; positive regulation of stress fiber assembly; regulation of actin cytoskeleton organization; small GTPase-mediated signal transduction; cytoplasmic microtubule organization; cytoskeleton-dependent intracellular transport; positive regulation of phosphatidylinositol 3-kinase/protein kinase B signal transduction; regulation of cell population proliferation; regulation of neuron projection development; TOR signaling; signal transduction
Cellular component: centriole; centrosome; ciliary basal body; cytoplasmic vesicle; cytosol; endoplasmic reticulum; Golgi apparatus; lamellipodium; membrane; plasma membrane; cytoplasm; cell leading edge
Genetic constraint (gnomAD): Loss-of-function variants: 17 observed, 102.13 expected, observed/expected ratio (o/e) 0.17, 90% interval 0.11 to 0.25. The upper end of that interval is the gene's LOEUF score, 0.25, which puts it in group 1 of 6, group 1 being the genes least tolerant of losing a copy. Missense variants: 1,033 observed, 1,183.2 expected, observed/expected ratio (o/e) 0.87, 90% interval 0.83 to 0.92. Synonymous variants: 417 observed, 432.75 expected, observed/expected ratio (o/e) 0.96, 90% interval 0.89 to 1.04.
Homologues: Orthologues: chimpanzee CCDC88A (99% identical), dog CCDC88A (97% identical), macaque CCDC88A (97% identical), rabbit CCDC88A (96% identical), pig CCDC88A (96% identical), rat Ccdc88a (94% identical), mouse Ccdc88a (93% identical), guinea pig CCDC88A (89% identical), tropical clawed frog ccdc88a (76% identical), Drosophila melanogaster Girdin (23% identical), Caenorhabditis elegans grdn-1 (17% identical). Paralogues in human: CCDC88C (48% identical), CCDC88B (23% identical), HOOK3 (12% identical), HOOK1 (11% identical), HOOK2 (11% identical).
Diseases named in the same sentence as CCDC88A in open-access papers:
CCDC88A is named in the same sentence as 51 diseases in open-access papers, as found by Europe PMC text mining. Sharing a sentence is not in itself a finding about the gene and the disease. The quoted sentences say what the papers report.
breast carcinoma (4 papers, 2020 to 2024). "Knockdown of CCDC88A expression suppresses human pancreatic, skin, and breast cancer cell migration and invasion, and significantly inhibits primary tumorigenesis in vivo, suggesting that CCDC88A has a key role in cancer development." (PMID 37532779, 2023). "Together these findings suggest that TNTs in contact cultures could provide a route for breast cancer cells to borrow from MSCs certain RNAs and proteins, among which CCDC88A/GIV may be a central player in functional outcomes." (PMID 39480488, 2024).
colitis (2 papers, 2025). Inflammation of the colon. "Notably, CCDC88A is part of the niColAM gene signature, which emerges during the recovery phase of DSS-induced colitis." (PMID 40766554, 2025).
colorectal cancer (2 papers, 2014 to 2015). A primary or metastatic malignant neoplasm that affects the colon or rectum. "CCDC88A, also known as GIV or Girdin, codes for coiled-coil domain containing 88A, and was found to be more highly expressed in samples of colorectal cancers with liver metastasis compared to cancers without metastasis." (PMID 24504141, 2014).
glioblastoma (2 papers, 2023 to 2024). The most malignant astrocytic tumor (WHO grade IV). "Since CCDC88A appears to be essential for glioblastoma migration and invasion, and is associated with glioma malignancy, it has also been suggested as a novel therapeutic target in malignant glioma." (PMID 38630692, 2024). "Like CCDC88A, the third-ranked result, Zinc Finger Protein 7 (ZNF7), has been associated with glioblastoma." (PMID 38630692, 2024). "A researcher about glioblastoma have also confirmed that CCDC88A expression is closely related to tumour malignancy, including the histological grade and metastasis, as well as progression-free survival and overall survival." (PMID 37532779, 2023).
glioma (2 papers, 2022 to 2024). A benign or malignant brain and spinal cord tumor that arises from glial cells (astrocytes, oligodendrocytes, ependymal cells). "An example of a changed diagnosis includes the re-classification of a pleomorphic xanthoastrocytoma (P2830) to an infant-type hemispheric glioma, generated by an intrachromosomal deletion on chromosome 2p adjoining exons 1–12 of the CCDC88A gene with ALK exons 20–29 reported previously." (PMID 35449451, 2022).
acute lymphoblastic leukemia (1 paper, 2018). Leukemia with an acute onset, characterized by the presence of lymphoblasts in the bone marrow and the peripheral blood. "Some of these genes have already been shown to play a role in hematologic malignancies, including CLL (Pim-2, Met, Rgs16, Ccdc88a, Zcchc18, Clip3), diffuse large B cell lymphoma, follicular lymphoma (Vav3), acute lymphoblastic leukemia (ALL) (Itm2a, Chst1) or acute myeloid leukemia (AML) (Chd3)." (PMID 30271400, 2018).
brain tumor (1 paper, 2024). "Additionally, CCDC88A has been linked to brain tumor stem cell stemness, mTORC1 signaling, DNA damage-induced cancer cell apoptosis, and cell cycle progression and appears to affect the sensitivity of cancer cells to therapeutics." (PMID 38630692, 2024).
Epileptic encephalopathy (1 paper, 2024). A condition in which epileptiform abnormalities are believed to contribute to the progressive disturbance in cerebral function. "The Coiled-Coil Domain-Containing Protein 88 A (CCDC88A) gene encodes the actin-binding protein Girdin, which plays important roles in maintaining the actin cytoskeleton and in cell migration and was recently associated with a specific form of epileptic encephalopathy." (PMID 39334473, 2024).
leukemia (1 paper, 2014). A malignant (clonal) hematologic disorder, involving hematopoietic stem cells and characterized by the presence of primitive or atypical myeloid or lymphoid cells in the bone marrow and the blood. "Taken together, through the initial screening studies in LCLs and further functional validation in leukemia cell lines, we found that the expression of three genes, CCDC88A, CTBP2, and SOCS4, were involved in HHT-induced response." (PMID 25628645, 2014). "Functional validation using siRNA knockdown in leukemia cell lines showed that knocking down CCDC88A, CTBP2, SOCS4 genes in U937 and K562 cells significantly altered HHT cytotoxicity." (PMID 25628645, 2014).
pancreatic ductal adenocarcinoma (1 paper, 2020). An infiltrating adenocarcinoma that arises from the epithelial cells of the pancreas. "CCDC88A, a substrate of the threonine/serine kinase Akt, was identified as a participator in the migration and invasiveness of pancreatic ductal adenocarcinoma (PDAC) cells." (PMID 32282333, 2020).
cancer (21 papers, 2013 to 2025). A tumor composed of atypical neoplastic, often pleomorphic cells that invade other tissues. "To determine whether CCDC88A expression might play a crucial role in the outcome of PDAC through modulation of the migration and invasiveness of cancer cells, or through its association with Akt, we next evaluated the role of CCDC88A in the control of PDAC cell migration and invasion." (PMID 27919290, 2016). "The upregulation of CCDC88A during cancer progression and wound healing has been reported as being essential for cell migration during both processes." (PMID 38630692, 2024). "Although conventional markers of normal pluripotent stem cells remained unchanged during serum depravation in both cells, markers of cancer stem cells followed the same pattern as CCDC88A." (PMID 38312224, 2024). "Based on these studies, it is deduced that CCDC88A is involved in tumor progression of several cancer types, such as breast, colon, and cervical cancer." (PMID 37532779, 2023). "Among these 50 predicted target genes, Girdin (also named CCDC88A) attracted our attention because of its critical role in the migration and invasion of cancer cells." (PMID 32583631, 2020). "The phosphorylation of CCDC88A by Akt occurs at the leading edge, which is required for directional cell migration and which, in the case of cancer cells, ultimately leads to invasion and metastasis." (PMID 27919290, 2016). "Besides being of interest due to its involvement in cancer and epithelial regeneration/repair, the role of CCDC88A in cell aging has also garnered interest due to its function as a direct downstream mediator of Akt signaling." (PMID 38630692, 2024). "The second-ranked gene, Coiled-Coil Domain Containing 88A (CCDC88A), has also been associated with cancer and aging and is involved in various biological processes, including tumor angiogenesis, cancer migration and invasion, tumor metastasis, and epithelial wound healing." (PMID 38630692, 2024). "In cancer and wound healing, STAT3 directly targets and upregulates CCDC88A, which also enhances the activation of STAT3 via a positive feedback loop." (PMID 38630692, 2024). "CCDC88A is a key modulator of the AKT-mTOR signaling pathway and CNKSR1 promotes invasion of cancer cells through NFκB dependent signaling (Fritz and Radziwill, 2010)." (PMID 30042785, 2018). "Thus, CCDC88A is a novel component of the phosphatidylinositol 3-kinase (PI3-K)⁄Akt signaling pathway, which is a core-signaling transduction pathway in cancer." (PMID 27919290, 2016).
tumor (14 papers, 2015 to 2024). "The expression levels of CCDC88A were higher in tumor tissues from clinical samples, whereas those of miR-199b-3p were lower." (PMID 37532779, 2023). "Taken together, the results indicated that CCDC88A regulated by miR-199b-3p induced tumor proliferation and invasion in OS via the EMT and Wnt/beta-catenin signaling pathways." (PMID 37532779, 2023). "Several reports have suggested that CCDC88A is involved in tumor progression." (PMID 37532779, 2023).
infectious disease (1 paper, 2019). A disorder directly resulting from the presence and activity of a microbial, viral, or parasitic agent in humans. "The identification of exosomal proteins, such as Serpin A3-7, CCDC88A and INHBA may be harbingers of additional factors that exacerbate infectious disease and metabolic dysfunction, which have long-been associated with reproductive failure." (PMID 31554846, 2019).
CCDC88A also shares sentences with these, for which no sentence is quoted: pancreatic cancer (3 papers); atherosclerosis (2); hepatocellular carcinoma (2); infection (2); osteosarcoma (2); Sepsis (2); acute myeloid leukemia (1); adenoma (1); airway allergy (1); Allergy (1); anaplastic thyroid carcinomas (1); bipolar disorder (1); breast tumor (1); colon carcinoma (1); Crohn disease (1); cyst (1); diffuse large B-cell lymphoma (1); follicular lymphoma (1); hypersomnia (1); Hypsarrhythmia (1); infertile (1); insulinoma (1); liver cancer (1); liver fibrosis (1); lung adenocarcinoma (1); lung carcinoma (1); lung squamous cell carcinoma (1); male infertility (1); malignant glioma (1); metastatic cancers (1).
A further 8 diseases each share a sentence with CCDC88A in 1 paper.